OOSP4A (oocyte secreted protein family member 4A)
Gene: Protein-coding gene on chromosome 11 (59,964,033 to 59,970,343, forward strand). Ensembl gene ENSG00000285010.
Subcellular location: Secreted
Gene Ontology:
Cellular component: extracellular region
Homologues: Orthologues: macaque OOSP4A (93% identical), rabbit OOSP4A (52% identical).